P4HA2 (prolyl 4-hydroxylase subunit alpha 2)
Diseases named in the same sentence as P4HA2 in open-access papers (continued):
Sharing a sentence is not in itself a finding about the gene and the disease.
colorectal cancer (5 papers, 2019 to 2025). A primary or metastatic malignant neoplasm that affects the colon or rectum. "P4HA2 has been implicated in various malignant tumors; however, its expression and functional role in colorectal cancer (CRC) remain poorly elucidated." (PMID 38857058, 2024). "Then, immunohistochemical analysis of 34 matched tumor and nontumor tissues was carried out to comprehensively characterize P4HA2 expression in colorectal cancer tissues, which confirmed the increased expression of P4HA2 in cancer tissues." (PMID 40406250, 2025). "The results showed that P4HA2 promotes the development of colorectal cancer, but the specific mechanism of P4HA2-mediated colorectal cancer development has not been elucidated." (PMID 40406250, 2025). "The results revealed that P4HA2 was notably upregulated in the colorectal cancer cell lines compared with the normal HIEC cell line." (PMID 40406250, 2025). "The findings revealed that P4HA2 was highly expressed in colorectal cancer cells and tissues, which was consistent with the results of the bioinformatics analysis." (PMID 40406250, 2025). "Analysis of the data from the TCGA database suggested that high P4HA2 expression in colorectal cancer specimens predicts a poor outcome in patients with colorectal cancer." (PMID 40406250, 2025). "In conclusion, P4HA2 emerges as a potential prognostic biomarker and promising therapeutic target in colorectal cancer." (PMID 38857058, 2024). "In conclusion, P4HA2 may promote the development of colorectal cancer by mediating immune regulation, but this study has several limitations, and the deeper mechanisms of immune regulation require further experimental investigation." (PMID 40406250, 2025). "Collectively, the data above suggest that P4HA2 may act as an oncogene in colorectal cancer tumorigenesis and progression." (PMID 40406250, 2025). "Since KRAS mutations occur frequently in colorectal cancer, we asked whether SLUG&P4HA2 overexpression may contribute to poor prognosis in KRAS mutated CRC." (PMID 38522060, 2024). "The results of the positive and negative bidirectional functional experiments, such as the CCK8, Transwell, and scratch assays, suggest that P4HA2 promotes colorectal cancer cell proliferation and migration in vitro and that it may have biological effects on colorectal cancer regulation." (PMID 40406250, 2025). "In colorectal cancer (CRC), P4HA2 exhibited overexpression, and elevated levels of P4HA2 expression were associated with an unfavorable prognosis." (PMID 38857058, 2024). "P4HA2 may affect the STAT1/PD-L1 pathway to promote the development and inhibit antitumor immunity of colorectal cancer by binding to and downregulating the expression of STAT1, which may reveal a new pathogenic mechanism." (PMID 40406250, 2025). "Nevertheless, research has not been able to establish the role of P4HA2 in colorectal cancer." (PMID 40406250, 2025). "HCT8 colorectal cancer cells with high P4HA2 expression were selected for gene knockdown, SW480 cells with low P4HA2 expression were selected for P4HA2 overexpression, and stably transfected cell lines with shP4HA2 interference and P4HA2 overexpression were constructed." (PMID 40406250, 2025). "Furthermore, we examined P4HA2 expression levels in 54 pairs of CRC tissues and matched nontumor tissues, which also revealed that P4HA2 was overexpressed in human colorectal cancer tissues compared with matched nontumor tissues." (PMID 40406250, 2025).
head and neck squamous cell carcinoma (5 papers, 2019 to 2024). A squamous cell carcinoma that arises from any of the following anatomic sites: lip and oral cavity, nasal cavity, paranasal sinuses, pharynx, larynx, and salivary glands. "In addition, P4HA1 and P4HA2 are confirmed hypoxia-associated genes and associated with poor prognosis in head and neck squamous cell carcinoma." (PMID 31467922, 2019). "We previously showed that p-EMT genes such as SERPINE1, ITGA5, TGFBI, P4HA2, CDH13, and LAMC2 are potent poor prognostic markers in head and neck squamous cell carcinoma (HNSCC) patients by bioinformatic analysis." (PMID 34294795, 2021).
papillary thyroid cancer (5 papers, 2011 to 2025). "P4HA2 encodes a key enzyme involved in collagen synthesis, and its over-expression has been previously reported in papillary thyroid cancer." (PMID 21989116, 2011).
lymph node metastasis (4 papers, 2020 to 2024). "Further analysis showed that P4HA2 expression is associated with sex, lymph node metastasis, and tumor grade." (PMID 36403427, 2022). "The result of this study showed that SLUG and P4HA2 were significantly higher in association with adverse prognostic factors: presence of lympho-vascular invasion, perineural invasion, higher tumor budding, tumor stage, presence of lymph node metastasis, and presence of distant metastasis." (PMID 38522060, 2024). "Lymph node metastasis (p=0.002, HR=2.388), poor differentiation (p=0.038, HR=1.863), advanced FIGO stage (p=0.019, HR=2.501) and high P4HA2 expression (p=0.024, HR=2.709) were significantly associated with poor survival." (PMID 32226497, 2020). "Additionally, semi-quantitative scoring analysis revealed a significant correlation between P4HA2 expression and clinical stage, pathological grades, and lymph node metastasis." (PMID 38951593, 2024). "Additionally, the UALCAN database indicates a significant correlation between P4HA2 expression and clinical stage, pathological grades, and lymph node metastasis." (PMID 38951593, 2024). "However, patients with high P4HA2 expression had a higher rate of lymph node metastasis, more advanced FIGO stage and poorer histological grade." (PMID 32226497, 2020).
melanoma (4 papers, 2016 to 2025). A malignant, usually aggressive tumor composed of atypical, neoplastic melanocytes. "As a positive control, we included P4ha2, which is prognostic of worse clinical outcomes in melanoma and associated with metastasis in other cancers." (PMID 31949145, 2020). "In another study, high P4HA2 mRNA levels were reported to correlate with poor prognosis in a dataset comprised mostly of melanoma metastases." (PMID 32053263, 2020). "Altogether, therapeutic targeting of P4HA1 (and P4HA2) is an interesting possibility for the treatment of aggressive melanomas, and other cancers, but more specific inhibitors, are still needed." (PMID 32053263, 2020). "Ectopic expression of P4HA2 and P4HA3 has opposing effects on melanoma growth, P4HA2 promoting and P4HA3 inhibiting proliferation of melanoma cell lines." (PMID 27461275, 2016). "To seek mechanistic correlates of the proposed differences between P4HA1/P4HA2 and P4HA3, we modulated expression of P4HA2 and P4HA3 in melanoma cell lines using ectopic expression and knock-down." (PMID 27461275, 2016).
myopia (4 papers, 2022 to 2026). "For non-syndromic genes (P4HA2, LOXL3), milder phenotypes may reflect early myopia progression, which could worsen with age or environmental triggers." (PMID 41259386, 2025).
prostate carcinoma (4 papers, 2014 to 2025). A carcinoma that arises from epithelial cells of the prostate gland. "However, P4HA2 mRNA expression levels were relatively lower than P4HA1 in malignant prostate cancer tissues and cell lines." (PMID 25115393, 2014).
breast tumors (3 papers, 2010 to 2023). "Furthermore, deletions of chromosome regions harboring GPM6 (4q34.2), CASP3 (4q35.1), and P4HA2 (5q23.3) have been shown to be associated with breast tumors from BRCA1 mutation carriers." (PMID 20174566, 2010). "This is the first report of IHC staining for P4HA2 in any human breast tumour cohort to our knowledge." (PMID 30410060, 2018). "In addition, they described that HIF-1α plays a critical role in collagen biogenesis in breast tumors by upregulating the expression of P4HA1, P4HA2, PLOD1, and PLOD2 hydroxylases as well as the lysyl oxidase family members LOX, LOXL2, and LOXL4." (PMID 37686617, 2023).
inflammatory bowel disease (3 papers, 2015 to 2021). A spectrum of small and large bowel inflammatory diseases of unknown etiology. "The index SNP at chromosome 5q31, rs715285, maps to an intergenic region flanked by the genes CSF2 and P4HA2 and this region has been reported to be a susceptibility locus for multiple immune-related diseases including juvenile idiopathic arthritis, inflammatory bowel disease (IBD) and asthma." (PMID 25651891, 2015). "At a false discovery rate (FDR) of 5%, we observed a significant enrichment of SLC22A4, SLC22A5, and P4HA2 genes for Crohn’s disease and inflammatory bowel disease (IBD)." (PMID 26053627, 2015).
liver fibrosis (3 papers, 2020 to 2025). "Functionally, HBx-elevated P4HA2 increased collagen deposition in the liver both in vivo and in vitro, contributing to liver fibrosis and cancer progression." (PMID 40406250, 2025). "The overexpression of P4HA2 mediated by down-regulation of miR-30e accelerates the collagen deposition in the liver in vivo and in vitro, ultimately leading to liver fibrosis and the growth of liver cancer." (PMID 34456908, 2021). "Interestingly, they found that HBx accelerates the collagen deposition in liver fibrosis through modulation of miR-30e targeting P4HA2 mRNA." (PMID 32206612, 2020).
lung adenocarcinoma (3 papers, 2019 to 2024). A carcinoma that arises from the lung and is characterized by the presence of malignant glandular epithelial cells. "P4HA2 was more highly expressed in fibroblasts than in epithelial cells in normal lung and lung adenocarcinoma tissues (p < 0.001)." (PMID 36403427, 2022). "Loss or methylation of RASSF1A leads to constitutive YAP activity, which together with mechanical properties of extracellular matrix via P4HA2 drives cancer stem‐like re‐programming and metastatic progression in lung adenocarcinoma." (PMID 31268606, 2019). "Interestingly, in vivo cell growth assays show that targeting P4HA2-mTOR significantly suppresses lung adenocarcinoma cell growth." (PMID 38654109, 2024).
ovarian carcinoma (3 papers, 2023 to 2026). A malignant neoplasm originating from the surface ovarian epithelium. "Our results indicate that LINC00240 and P4HA2 are significantly overexpressed, while miR-30c-5p is downregulated in ovarian cancer." (PMID 42108519, 2026). "This study investigates the expression and functional role of LINC00240, miR-30c-5p, and P4HA2 in ovarian cancer pathogenesis." (PMID 42108519, 2026). "Using datasets GSE66957 and the GEPIA database, we assessed LINC00240 expression levels and employed quantitative real-time polymerase chain reaction (qRT-PCR) to evaluate the expression of LINC00240, miR-30c-5p, and P4HA2 in ovarian cancer samples." (PMID 42108519, 2026). "Furthermore, LINC00240 modulates ovarian cancer malignancy by regulating P4HA2 expression through binding with miR-30c-5p." (PMID 42108519, 2026). "Abnormal P4HA2 expression indicates a poor outcome in liver, cervical, and ovarian cancers." (PMID 37248456, 2023).
breast ductal carcinoma in situ (2 papers, 2018 to 2020). "P4HA2 has been recently reported to play a role in the progression of breast ductal carcinoma in situ (DCIS)." (PMID 32500033, 2020). "This study aims to evaluate the prognostic significance of P4HA2 in breast ductal carcinoma in situ (DCIS)." (PMID 30410060, 2018).
colon cancer (2 papers, 2025). "Subsequently, we assessed the impact of the KynA/P4HA2 axis on colon cancer proliferation and liver metastasis in mice subjected to sleep deprivation." (PMID 39920992, 2025). "P4HA2 overexpression reversed KynA’s inhibitory effects on colon cancer cell proliferation and migration." (PMID 39920992, 2025). "In conclusion, our results validate the role of the KynA/P4HA2/VHL/HIF-1α/HILPDA axis in promoting colon cancer progression due to sleep deprivation." (PMID 39920992, 2025). "To investigate the presence of KynA/P4HA2/VHL/HIF-1α/HILPDA axis in mediating the effects of sleep deprivation on colon cancer, we underwent rescue experiments." (PMID 39920992, 2025). "To clarify the role of P4HA2 in CRC, we further detected P4HA2 expression in five colon cancer cell lines (HCT8, SW620, HT29, SW480, and LoVo cells) and one normal human intestinal epithelial cell line (HIEC cells)." (PMID 40406250, 2025). "Transfection of colon cancer cells with si-P4HA2#1 and CHX treatment revealed that HIF-1α stability decreased in the P4HA2 knockdown group." (PMID 39920992, 2025). "In conclusion, our results validate the role of the P4HA2/HIF-1α/HILPDA signaling axis in promoting colon cancer progression." (PMID 39920992, 2025). "Similarly, the impact of the KynA/P4HA2/HILPDA axis on colon cancer cell proliferation and migration was confirmed." (PMID 39920992, 2025). "However, colon cancer cells overexpressing P4HA2 showed resistance to KynA treatment, increasing in xenograft size and weight." (PMID 39920992, 2025). "Furthermore, we used GEO dataset GSE10950 and tissue chips to assess P4HA2/VHL/HIF-1α/HILPDA signaling axis on colon cancer." (PMID 39920992, 2025). "Mechanistically, KynA downregulates the expression of P4HA2 to promote the ubiquitination and degradation of HIF-1α, which leads to a decrease in the transcription of HILPDA, and ultimately leads to an increase in lipolysis of colon cancer cells." (PMID 39920992, 2025).
gastric cancer (2 papers, 2022 to 2025). A primary or metastatic malignant neoplasm involving the stomach. "Evidence from another study suggested that PCGEM1 also improves the invasive ability of gastric cancer cells by increasing the level of prolyl 4-hydroxylase subunit alpha 2 (P4HA2)." (PMID 35055115, 2022).
glioblastoma (2 papers, 2022). The most malignant astrocytic tumor (WHO grade IV). "Recently, it was demonstrated that prolyl-4-hydroxylase subunit 2 (P4HA2), which is involved in collagen biogenesis, was one of the key players in the tumor microenvironment, and that P4HA2 promoted EMT, cell proliferation, and invasion in glioblastoma." (PMID 35053605, 2022).
liver cancer (2 papers, 2022 to 2023). An epithelial or non-epithelial malignant neoplasm that arises from the liver. "Low P4HA2 expression in normal controls but high in liver cancer tissues was also observed in immunohistochemistry staining results retrieved from the Human Protein Atlas database, agreeing with those from the UALCAN database." (PMID 37248456, 2023). "In addition, the knockdown of both P4HA2 and PYCR1 reduced cell proliferation of cervical and liver cancer cells, respectively." (PMID 35086476, 2022).
metastatic disease (2 papers, 2024 to 2025). "IHC results showed that P4HA2 knockdown also reduced the expression of Ki67 in lung metastatic tumors." (PMID 40379610, 2025).
pancreatic cancer (2 papers, 2023 to 2024). "On the other hand, our result was contradictory with a study on pancreatic cancer which demonstrated that low expression of P4HA2 was correlated with short DFS and OS." (PMID 38522060, 2024).
Alzheimer disease (1 paper, 2024). A progressive, neurodegenerative disease characterized by loss of function and death of nerve cells in several areas of the brain leading to loss of cognitive function such as memory and language. "Existing research has suggested that P4HA2 plays a role in many biological processes, including collagen maturation, epithelial-mesenchymal transition, and the deposition of amyloid β in Alzheimer's disease, and is vital in promoting tumor progression." (PMID 38951593, 2024).
autosomal dominant myopia 25 (1 paper, 2025). "Interestingly, the P4HA2 gene is associated with autosomal dominant myopia 25 (MYP25) and encodes a critical component of prolyl 4-hydroxylase, an enzyme essential for collagen hydroxylation and scleral stability." (PMID 41259386, 2025).
chondrosarcoma (1 paper, 2019). A malignant cartilaginous matrix-producing mesenchymal neoplasm arising from the bone and soft tissue. "The expression of P4HA1/P4HA2 affected by hypoxia was also reported in chondrosarcoma cells and soft tissue sarcomas." (PMID 31467922, 2019).
colon adenocarcinoma (1 paper, 2021). "All of the eight immune checkpoints were significantly correlated with the P4HA2 expression in BRCA, COAD (colon adenocarcinoma), LGG, and PRAD." (PMID 34249930, 2021).
diffuse large B-cell lymphoma (1 paper, 2024). "Notably, within diffuse large B-cell lymphoma (DLBCL) tissues, P4HA2 is expressed in tumor cells in approximately half of the tumor samples, while exhibiting heightened expression in stromal cells surrounding tumor in the majority of tumor samples." (PMID 38909089, 2024).
giant cell arteritis (1 paper, 2024). "It is plausible that the influence of the P4HA2 gene is specific to a particular subtype of patients with giant cell arteritis, who are potentially under-represented in our study." (PMID 38734017, 2024). "Unlike previous findings, our study did not observe the reported association between P4HA2 and giant cell arteritis, a gene that was suggested to be related to the artery remodelling process through the plasmin pathway." (PMID 38734017, 2024).
human papillomavirus infection (1 paper, 2024). "P4HA2 is significantly associated with proteoglycans in cancer, human papillomavirus infection, PI3K-Akt signaling pathway, HIF-l signaling pathway, and glycolysis/gluconeogenesis." (PMID 38806556, 2024).
invasive carcinoma (1 paper, 2018). A carcinoma that is not confined to the epithelium, and has spread to the surrounding stroma. "P4HA2 expression was assessed immunohistochemically in malignant cells and surrounding stroma of a large DCIS cohort comprising 481 pure DCIS and 196 mixed DCIS and invasive carcinomas." (PMID 30410060, 2018).
lentivirus infection (1 paper, 2025). Virus diseases caused by the Lentivirus genus. "Cells with stable P4HA2 overexpression were generated via lentivirus infection, and P4HA2 overexpression was confirmed via qRT–PCR and Western blotting, demonstrating P4HA2 overexpression by more than nine-fold." (PMID 40406250, 2025).
non-small cell lung carcinoma (1 paper, 2023). A group of at least three distinct histological types of lung cancer, including non-small cell squamous cell carcinoma, adenocarcinoma, and large cell carcinoma. "Interestingly, two target genes identified in a previously conducted microarray study to be up-regulated by RASSF1C in breast and non-small cell lung cancer (NSCLC) cells are prolyl 4-hydroxylase alpha-2 (P4HA2) and procollagen-lysine, 2-oxoglutarate 5-dioxygenase 2 (PLOD2)." (PMID 36826019, 2023).
osteogenesis imperfecta (1 paper, 2024). Osteogenesis imperfecta (OI) comprises a heterogeneous group of genetic disorders characterized by increased bone fragility, low bone mass, and susceptibility to bone fractures with variable severity. "Similarly, the p3h1, whose human ortholog is involved in osteogenesis imperfecta and p3h3 genes code for prolyl-3-hydroxylases, while the p4ha1a and the p4ha2 genes code for prolyl-4-hydroxylases whose mutation in mouse causes impaired ECM, chondrodysplasia, and kyphosis." (PMID 38547142, 2024).
osteosarcoma (1 paper, 2023). A usually aggressive malignant bone-forming mesenchymal neoplasm, predominantly affecting adolescents and young adults. "Among them, MAN2B1, P4HA2, ANPEP, BCAT1, CTSS, and DAPK1 were significantly correlated with the prognosis of patients with osteosarcoma." (PMID 37457661, 2023).
rosacea (1 paper, 2025). A chronic erythematous skin disorder that affects the face. "Through the comprehensive analysis of rosacea of three tissues, SMR analysis identified three druggable genes in human blood that were causally associated with rosacea‐related traits (p‐FDR < 0.05), including P4HA2, IRF1, and SLC22A5." (PMID 40635520, 2025).